SHANK2 (SH3 and multiple ankyrin repeat domains 2)
Description:
Seems to be an adapter protein in the postsynaptic density (PSD) of excitatory synapses that interconnects receptors of the postsynaptic membrane including NMDA-type and metabotropic glutamate receptors, and the actin-based cytoskeleton. May play a role in the structural and functional organization of the dendritic spine and synaptic junction.
Synonyms: CortBP1; PROSAP1; CTTNBP1; SHANK; SPANK-3; AUTS17
Tractability: Antibody: UniProt places it where antibodies can reach, with medium confidence; its Gene Ontology location is reachable by antibodies, with medium confidence; the Human Protein Atlas places it where antibodies can reach. PROTAC: its protein half-life has been measured.
Gene: Protein-coding gene on chromosome 11 (70,467,805 to 71,252,844, reverse strand). Ensembl gene ENSG00000162105.
Subcellular location: Apical cell membrane; Cytoplasm; Synapse; Postsynaptic density; Cell projection, growth cone; Cell projection, dendritic spine
Subcellular location (Human Protein Atlas): Nuclear speckles; Vesicles; Nucleoplasm; Plasma membrane
Pathways (Reactome):
Neuronal System: Neurexins and neuroligins
Gene Ontology:
Molecular function: protein binding; ionotropic glutamate receptor binding; synaptic receptor adaptor activity
Biological process: adult behavior; learning; negative regulation of hippo signaling; positive regulation of cell population proliferation; social behavior; vocalization behavior; associative learning; long-term synaptic depression; long-term synaptic potentiation; synapse assembly; synapse organization; cognition
Cellular component: apical plasma membrane; brush border membrane; ciliary membrane; cytosol; dendritic spine; growth cone; neurofilament; neuron projection; neuronal cell body; photoreceptor inner segment; photoreceptor outer segment; plasma membrane; postsynaptic density; postsynaptic membrane; cytoplasm; synapse
Genetic constraint (gnomAD): Loss-of-function variants: 36 observed, 114.08 expected, observed/expected ratio (o/e) 0.32, 90% interval 0.24 to 0.42. The upper end of that interval is the gene's LOEUF score, 0.42, which puts it in group 1 of 6, group 1 being the genes least tolerant of losing a copy. Missense variants: 1,743 observed, 2,135.9 expected, observed/expected ratio (o/e) 0.82, 90% interval 0.78 to 0.85. Synonymous variants: 882 observed, 914.95 expected, observed/expected ratio (o/e) 0.96, 90% interval 0.91 to 1.02.
Gene-disease validity (ClinGen):
ClinGen rates the evidence that SHANK2 causes each of these diseases.
complex neurodevelopmental disorder (autosomal dominant): Definitive. A disorder that involves more than one phenotype associated with the central nervous system, including but not limited to intellectual disability, autism, and seizures (epilepsy).
Homologues: Orthologues: chimpanzee SHANK2 (99% identical), macaque SHANK2 (98% identical), guinea pig SHANK2 (91% identical), dog SHANK2 (90% identical), mouse Shank2 (89% identical), rabbit SHANK2 (88% identical), rat Shank2 (87% identical), tropical clawed frog shank2 (74% identical), pig SHANK2 (58% identical), Drosophila melanogaster Prosap (21% identical), Caenorhabditis elegans shn-1 (17% identical). Paralogues in human: SHANK3 (44% identical), SHANK1 (43% identical).
Diseases named in the same sentence as SHANK2 in open-access papers:
SHANK2 is named in the same sentence as 75 diseases in open-access papers, as found by Europe PMC text mining. Sharing a sentence is not in itself a finding about the gene and the disease. The quoted sentences say what the papers report.
autism (90 papers, 2010 to 2026). Persistent deficits in social interaction and communication and interaction as well as a markedly restricted repertoire of activity and interest as well as repetitive patterns of behavior. "Overall, SHANK2 disorder is associated with developmental and adaptive functioning delays, high rates of autism, including sensory symptoms and repetitive behaviors, and ADHD." (PMID 40307697, 2025). "Three additional SHANK2 variants in the PDZ domain had been observed in patients (p.V717F in an autism case, p.S610Y and p.N690S in schizophrenia patients)." (PMID 36450866, 2024). "Our study provides novel insights on a SHANK2 mutation derived from autism patient and highlights SHANK2B significance in ALDH1A1 negative DA neuron." (PMID 38704506, 2024). "Here, we report a point mutation on SHANK2, which is found in a patient with autism, located on exon of the SHANK2B transcript variant (NM_133266.5), hereby SHANK2BY29X." (PMID 38704506, 2024). "For instance, the simultaneous downregulation of both Shank2 and Shank3 proteins was recently shown to impair social memory, a feature strictly associated with autism." (PMID 37019889, 2023). "Human genetic studies have implicated SHANK2 in ASDs, and previous rodent experiments have reported autism-like behaviors in two different lines of Shank2 mutant mice as well as impaired social and cognitive behaviors in Shank2Δe24 mice." (PMID 36768529, 2023). "Human genetic studies have implicated SHANK2 in a wide spectrum of neurodevelopmental conditions, including autism symptoms, intellectual disability, hyperactivity, and anxiety." (PMID 36768529, 2023). "Shank2-deficient mice (Shank2−/−) displayed abnormal and repetitive behaviors, as well as autism-like social deficit behaviors." (PMID 35216408, 2022). "Abnormalities within the three SHANK genes are detected in the whole spectrum of autism and a higher cognitive impairment is observed when mutations are present in the SHANK3 and SHANK2 genes compared to SHANK1." (PMID 36100669, 2022). "SHANK2 mutation has been recently linked to autism, and SHANK2 expression is mostly restricted to the nervous system." (PMID 32661924, 2021). "Variants in neuroligin 1 and SHANK2 have been implicated in susceptibility to autism, while variants in neuroligin 3 have been implicated in Asperger syndrome and autism." (PMID 34610269, 2021). "Patients with mutations in SHANK2 show autism-like behaviors, developmental delay, and intellectual disability." (PMID 34899182, 2021). "Many of the selected genes have been found to be associated with neurological diseases, including autism [SHANK2], chronic pain [CACNG2], epilepsy [CHRNB2], Huntington’s disease [GRIN3A], and neurodegenerative diseases [SYBU]." (PMID 32848578, 2020). "Another de novo mutation found in SHANK2 in an individual with autism (L1008P1009dup; LPdup) was still able to rescue the loss of EZ-associated PSDs (66.9% ± 3%)." (PMID 31597090, 2019). "In fact similar regional cerebellar differences to that observed in GLAST–/– and ET4–/– mice have been reported in Shank2-deficient mice that exhibit autism-like behaviour." (PMID 29741614, 2018). "Encoding and updating of virtual cued goal location memory was impaired in mice deficient in the postsynaptic scaffolding protein Shank2, a mouse model of autism that exhibits impaired spatial learning in a real environment." (PMID 28484738, 2017). "We found that many top associated a-DMSs, and their annotated gene were linked to diseases, such as SHANK2 (cg16069986 and cg16312514) which is related to autism, and CSRP3 (cg05895618) which is linked to cardiomyopathy." (PMID 28056824, 2017).
autism (continued). "Overall, SHANK2 disorder is associated with developmental and adaptive functioning impairments indicative of a likely high rate of ID, high rates of autism, including sensory symptoms and repetitive behaviors, and ADHD, all of which were also top caregiver concerns." (PMID 40307697, 2025). "In addition to autism, the SHANK2 gene has also been associated with schizophrenic behaviors and decreased bone mass in animal models." (PMID 40307697, 2025). "Accordingly, we speculated that SHANK2 loss-of-function in autism would be associated with abnormal sensory processing, especially in the auditory and visual pathways." (PMID 36768529, 2023). "There is a precedent for this, as although many disorders that feature ASD arise from heterozygous mutations, robust phenotypes are frequently only seen in mice homozygous for the mutation, such as has been observed in mouse models for autism-associated gene SHANK2." (PMID 34311771, 2021). "Among 760 ASD patients evaluated SHANK1 mutations were found in 0.04% and were present in males with normal IQ and autism, SHANK2 mutations were present in 0.17% of patients with ASD and mild intellectual disability and mutations in SHANK3 were present in 0.69% of the patients with ASD." (PMID 27458336, 2016). "Using a combination of genetic and functional approaches, we identified novel SHANK2 mutations including a de novo loss of one copy of the SHANK2 gene in a patient with autism and several mutations observed in patients that reduced neuronal cell contacts in vitro." (PMID 22346768, 2012). "Indeed several autism-associated genes that can be found at excitatory postsynapses, such as Shank2 and Shank3, MTs and ERK are Zn2+ binding, and Zn2+ regulated proteins." (PMID 23346059, 2012). "Mutations in SHANK2 were recently reported in several individuals with autism." (PMID 21695253, 2011). "Additionally, studies using neuronal cultures or transgenic mice have shown that spine density and/or shape were altered after genetic manipulation of proteins implicated in syndromic or non-syndromic autism, including neurexins/neuroligins, Shank2/3, Epac2, Tsc1/2, Ube3A and PTEN." (PMID 28258509, 2017). "In terms of neurodevelopmental, psychiatric, and behavioral features, 90% of participants carried a formal diagnosis of autism, replicating the prevalence of the two previous SHANK2 studies." (PMID 40307697, 2025). "Future research should be conducted in person to further assess autism symptoms in SHANK2 disorder and how they differ from idiopathic autism using gold-standard diagnostic assessments." (PMID 40307697, 2025). "An autism gene knockout model of the post-synaptic scaffolding proteins ProSAP1/Shank2 was shown to modify ultrasonic vocalization in both adult and pup mice in both a quantitative and qualitative manner." (PMID 40370017, 2025). "Only in SHANK2, missense mutations have been reported which alter residues close to, or in the PDZ domain: S610Y; N690S in schizophrenia cases, and V717F in autism." (PMID 36450866, 2024). "MoSeq, which previously had been used for pharmacological studies and research on a cerebellar-specific autism mouse model, was able to recognize genotype- and sex-specific behavioral syllables in Shank2−/− mice in our study." (PMID 39262819, 2024). "In this case, we cannot rule out an influence of hyperactivity on social deficits, as in some other mouse models of autism [e.g., Shank2/ProSAP1−/−mice:]." (PMID 38173978, 2023). "SHANK2 knockdown mice have also been proposed as an autism model, and its knockdown has been shown to induce deficits in sociability in naïve mice and reduce parental bond in dams." (PMID 37537543, 2023). "Shank2, a multidomain scaffolding protein enriched at excitatory neuronal synapses, has been shown to regulate autism-like social behaviors." (PMID 36690791, 2023).
autism (continued). "The insufficient activation of glycinergic interneurons because of disrupted excitatory synapses observed in Shank2−/− mice is a new mechanism for abnormal pain processing in autism." (PMID 37316943, 2023). "Anxiety is an associated symptom of autism and a phenotype detected in other ASD mouse models such as Shank1, Shank2, and Shank3 KO mice." (PMID 35682762, 2022). "We generated a Shank2-Shank3 double knockout mouse that is showing severe autism related core symptoms, as well as a broad spectrum of comorbidities." (PMID 36100669, 2022). "Shank2 and Fmr1 mutant mouse models of autism display hyperactivity that is increased by the administration of MPH." (PMID 33785025, 2021). "Mice with deletion of several other genes (Shank2, mGluR5 and Lom4) in PV-neurons exhibit autism-related behaviors of varying severity, supporting that the function of PV-neurons is an important determinant of autism behaviors." (PMID 33504340, 2021). "Of note, the loss of Sapap3 causes obsessive-compulsive behavioral traits in mice, which are typical in individuals with autism and have also been described in Shank2 Δex7−/− mice." (PMID 30023428, 2018). "Infection-related downregulation was also observed for several synaptic proteins previously identified in genetic studies of neuropsychiatric disorders like bipolar disorder (neurocan), major depression (Homer-1; Piccolo), or autism (Shank2)." (PMID 30068357, 2018). "Shank2 Δe6-7–/– mice exhibit hyperactivity and autism-like behavior too, though with a reduced NMDA/AMPA ratio and selectively decreased NMDAR-mediated synaptic transmission, as well as severely impaired LTP and LTD." (PMID 30627085, 2018). "In this sample, we detected a 421.2 kb deletion within SHANK2 in patient AU038_3 with autism and moderate ID (see patient section in Materials and Methods)." (PMID 22346768, 2012). "Here, following the discovery of two de novo SHANK2 deletions by the Autism Genome Project, we identified a novel 421 kb de novo SHANK2 deletion in a patient with autism." (PMID 22346768, 2012). "Although no cases of mutations in SHANK1 have yet been identified in individuals with autism, SHANK1 is a member of the SHANK gene family, in which mutations in SHANK2 and SHANK3 have been detected in several autistic individuals." (PMID 21695253, 2011). "Candidate genes for autism include the SHANK gene family, as mutations in SHANK2 and SHANK3 have been detected in several autistic individuals." (PMID 21695253, 2011). "Whether the rate of autism in SHANK2 disorder is truly this high, or if this represents a sample bias given autism is often a reason for referral for genetic testing, is unclear." (PMID 40307697, 2025). "Cells in the later pseudotime stage exhibited specific enrichment in synaptic pathways, characterized by the upregulation of several neuronal markers, including CUX2, glutamate metabotropic receptor genes (GRM1, GRM2, and GRM3), and several autism risk genes, including PTEN, SCN2A, and SHANK2." (PMID 39363111, 2024). "A previous study on autism-associated genes did not report evidence for sex-specific expression patterns of SHANK2 and SHANK3 in the adult human CTX." (PMID 37953224, 2023). "Interestingly, the genes contributing to the suppressed pathways that regulate the development of the central nervous system included SHANK2 and CNTNAP2, deletions of which are associated with autism and intellectual disability." (PMID 36084040, 2023).
autism (continued). "Studies have shown that two lines of Shank2 knockout mice altering different regions of the protein displayed similar autism behavioral phenotypes, which were different from bipolar-associated mania-like behavior exhibited in the third line of Shank2Δex24 knockout mice." (PMID 36768529, 2023). "In order to confirm the classifier’s accuracy and characterize burying events in high detail, we performed the marble burying test in three mouse models: Ube3am-/p+[Angelman syndrome (AS) model], Shank2−/− (autism model), and Sapap3−/− [obsessive-compulsive disorder (OCD) model] mice." (PMID 35288451, 2022). "LRFN2 knockout mice exhibited autism-like behavioural abnormalities and, similar to SHANK2 and ASB4, could be relevant in terms of pig feeding related behaviors." (PMID 36057580, 2022). "Reduction in social/non-social neuronal proportion in mPFC is a phenomenon that is shared by several autism mouse models, such as Shank2-KO and Cntnap2-KO mice, and therefore, may be causally related to the social impairment seen in IRSp53-KO mice." (PMID 36317872, 2022). "High levels of jumping behavior have been reported in Shank2 null, Sh3rf2 haploinsufficient, Camk2a-E183V, and Nlgn2 overexpression mice that model genetic risk factors for ASD and in the C58 inbred strain described as a mouse model of autism." (PMID 35227461, 2022). "SHANK genes (SHANK1, SHANK2, and SHANK3) encode synaptic folding proteins, and genetic manipulations that alter the expression of these proteins have been used to model the effects of genetic risk factors of autism." (PMID 32383208, 2020). "Mutations in SHANK2 and SHANK3 are highly associated with monogenetic forms of autism and PZD mice show behavioral alterations similar to SHANK mice modeling ASD by gene knockout." (PMID 29379414, 2017). "In our snRNA-seq dataset, of all tested diseases, genes associated with autism (DOID:12849) were overrepresented (Fisher’s exact test, OR = 10.2, Padj = 8.52 × 10−16) among the top 100 Purkinje cell marker genes, including RORA [fold change (FC) = 331.9], AUTS2 (FC = 43.1), and SHANK2 (FC = 13.8)." (PMID 37824616, 2023). "Among these genes, the SHANK family is of interest since mutations in each of the three members of this family (SHANK1, PROSAP1/SHANK2, and PROSAP2/SHANK3) have been identified in patients with autism, but with a gradient of severity." (PMID 30337855, 2018). "We expect that the autism kits with the probes covering the most recurrent CNVs in autism, 15q11-q13 and 16p11 regions together with SHANK3 and SHANK2 genes, have a detection rate of about 2-6%." (PMID 28357200, 2016). "Some autism candidate genes that have been identified so far, such as COMMD1, MTF1, MTs, ZnT5, ERK1, TrkB, Shank2, and Shank3, are influenced by Zn2+ or themselves involved in Zn2+ signaling and metal ion homeostasis." (PMID 23346059, 2012). "Cell type-specific deletions of Shank2 in the Purkinje cells of the cerebellum, in all parvalbumin-positive cells, and in CAMKIIA- and Viaat-positive excitatory and inhibitory neurons reflected distinct features of an autism-related phenotype." (PMID 37953224, 2023). "Given that SHANK2 and SHANK3 are major autism candidate-genes, their regulation via zinc may provide a link between genetic and non-genetic risk factors in ASD." (PMID 34741005, 2021). "In addition, decreased CYFIP1 mRNA levels were also found in leukocytes obtained from ASD diagnosed patients with Fragile X and in patients diagnosed with autism and carrying a deletion of SH3 and multiple ankyrin repeat domains 2 (SHANK2) gene." (PMID 30664619, 2019). "The individuals carrying a SHANK2 de novo deletion were diagnosed with autistic disorder or pervasive developmental disorder not otherwise specified (PDD-NOS) in combination with mild to moderate ID (mean IQ = 62±17)." (PMID 25188300, 2014).
autism (continued). "While SHANK1 has not been associated with autism, mutations in SHANK2 and SHANK3, other members of the SHANK gene family, appear in several individuals with autism." (PMID 21695253, 2011). "Relevant to the effect of MPH in Shank2- and Fmr1-deficient mice, hyperactivity of Trpm1-deficient mice may not be related to ADHD, but instead autism which is also one of the phenotypes of 15q13.3 microdeletion syndrome." (PMID 33785025, 2021).